AXL (AXL receptor tyrosine kinase)
Diseases named in the same sentence as AXL in open-access papers (continued):
Sharing a sentence is not in itself a finding about the gene and the disease.
gastric cancer (continued). "This study confirms phosphorylated AXL (pAXL) as a significant prognostic marker in gastric cancer (GC)." (PMID 39597836, 2024). "The in vitro experiments using recombinant Gas6 and a decoy-receptor of AXL showed that activation of Gas6-AXL signaling axis leads to the inhibition of apoptosis and exacerbation of AKT-dependent survival and invasion of gastric cancer cells." (PMID 37469409, 2023). "In the present study, tissue microarrays containing gastric cancer tissues were stained with MET and AXL antibodies, which showed the prognostic values of MET and AXL." (PMID 34766112, 2020). "In gastric cancer xenograft models, administration of LY2801653 significantly halted MKN45 tumor growth with inhibited MET and AXL phosphorylation activities, decreased cell proliferation and microvessel densities, and increased apoptosis in tumors." (PMID 34766112, 2020). "In another study, inhibition of AXL-NF-κB signaling pathway by ursolic acid markedly inhibited cell migration and reduced the expression of mesenchymal markers and EMT-related transcription factors in gastric cancer cells and xenografts." (PMID 37469409, 2023). "In addition, cabozantinib, a dual inhibitor of MET and AXL, decreased cell growth in both in vitro and in vivo models of HER2-amplified gastric cancer with acquired resistance to afatinib, a pan-HER inhibitor." (PMID 37469409, 2023). "Taken together, our data indicated that the dual MET/AXL inhibitor LY2801653 successfully targeted MET and AXL by killing tumor cells or affecting tumor microenvironment, representing a promising strategy for the treatment of gastric cancer." (PMID 34766112, 2020). "The results showed that CAFs are closely adjacent to cancer cells in gastric cancer tissues, and the interaction between CAFs and cancer cells promotes the progression of gastric cancer through the secretion of various cytokines and growth factors, such as GAS6 and AXL." (PMID 40485724, 2025). "However, the effect was not obvious in gastric cancer cells with moderate MET and AXL expression SNU719 cells." (PMID 34766112, 2020).
head and neck cancer (17 papers, 2015 to 2025). A primary or metastatic malignant neoplasm affecting the head and neck. "Targeting MET, vascular endothelial growth factor receptor (VEGFR) and AXL using cabozantinib resulted in decreased migration, invasion, and proliferation causing apoptotic cell death in naïve and therapy resistant head and neck cancer cells." (PMID 38891113, 2024). "Likewise, MMP-3 has been associated with vascular invasion in EC and AXL has been reported to induce MMP-3 expression in head and neck cancer cell invasion." (PMID 27764792, 2016). "The increased expression of AXL has been reported in several cancer types, such as lung, breast, and colorectal as well as head and neck cancer." (PMID 30140167, 2018). "Taken together, our patient-derived data and in vitro results suggest that, in head and neck cancer, AXL is important for the progression to more advanced tumor stages and is functionally involved in HNSCC cell motility." (PMID 28025482, 2016). "The AXL-specific inhibitor, R428, has been shown to inhibit cell growth and migration of erlotinib-resistant head and neck cancer cells as well as to resensitize these cells to erlotinib." (PMID 26573603, 2015). "More importantly, migration and invasion of head and neck cancer cells could be reduced by anti-AXL treatment with BGB324." (PMID 28025482, 2016). "Moreover, AXL overexpression is sufficient to induce resistance to the EGFR inhibitor cetuximab in head and neck cancer cell models." (PMID 27834845, 2016). "In addition to chemotherapy, AXL also promotes resistance to conventional radiotherapy in head and neck cancers." (PMID 27834845, 2016). "This review highlights the role of AXL, MET, and RON families of RTKs in tumor progression and resistance to anti-EGFR therapies, focusing on breast and head and neck cancers." (PMID 40560045, 2025). "We conclude that CCND1, AXL, CDKN2A, TERT, and EZH2 are the hub genes involved in cisplatin resistance in head and neck cancer that have significant mRNA expression and effect on overall survival." (PMID 36715825, 2023). "AXL overexpression has been reported to induce resistance to the EGFR inhibitor cetuximab in NSCLC and head and neck cancer cell models." (PMID 33396393, 2020). "In keeping with previous studies which identified high AXL expression and AXL-mediated oncogenic properties in OSCC and head and neck cancers, we found AXL to be highly expressed in our cell lines, whereas TYRO3 and MERTK levels were barely detectable." (PMID 28118606, 2017). "MGCD265 is an oral, multi-targeted, receptor tyrosine kinase inhibitor that targets MET, AXL, and PDGFR and is in clinical trials for non-small cell lung cancer (NSCLC), head and neck cancers, and advanced malignancies." (PMID 27655711, 2016). "AXL endows cancer cells with resistance to treatment through activation of PI3K/AKT pathway and up-regulation of programmed cell death ligand 1 (PD-L1) transcription in head and neck cancer cells, thereby inhibiting the immune killing effect of the body." (PMID 37328828, 2023). "Indeed AXL dimerization and phosphorylation of EGFR leads to the activation of phospholipase C gamma and protein kinase C that results in the activation of mTOR signaling to promote resistance to PI3K inhibition in head and neck cancer." (PMID 27834845, 2016).
renal carcinoma (15 papers, 2012 to 2025). A carcinoma arising from the epithelium of the renal parenchyma or the renal pelvis. "This analysis identified kinases implicated in advanced renal cancer including AXL, ALK1, and MET." (PMID 28418903, 2017). "In renal cancer, lncARSR functions as miRNA sponge to competitively bind with miR-34 and miR-449, which can up-regulate AXL/c-MET and activate STAT3, AKT, and ERK signaling." (PMID 31892841, 2020). "The claim was solely based on the lack of correlation between the tumor size and serum levels of AXL in renal cancer patients." (PMID 25551830, 2014). "Recently, the soluble fraction from the extracellular domain of AXL (sAXL) has been found in human plasma, and its level was correlated to poor prognosis in patients with renal cancer." (PMID 25551830, 2014). "Hence, the further investigation elucidating the mechanism by which STAMBPL1/AXL regulates resistance to sunitinib in renal cancer was needed in the future." (PMID 39527690, 2025). "In mouse models, cabozantinib significantly decreased the expression of PD-L1 on renal cancer cells via c-Met signaling inhibition; a similar effect is hypothesized to occur through AXL inhibition." (PMID 38541124, 2024). "It is believed that lncARSR or AXL/c-MET inhibitors may have curable potential in renal cancer treatment." (PMID 27713133, 2017). "Targeting the STAMBPL1/AXL axis significantly enhances the efficacy of sunitinib treatment and immunotherapy, hence it is worth exploring whether STAMPBP1 expression is associated with the prognosis in patients with renal cancer." (PMID 39527690, 2025). "In renal cancer, downregulation of AXL reduced phosphorylation of AKT but not phosphorylation of ERK." (PMID 34721022, 2021). "Exosomal lncARSR could be incorporated into exosomes and transmitted to sensitive cells and then promote sunitinib resistance via competitively binding miR‐34/ miR‐449 to facilitate AXL and c‐MET expression in renal cancer cells." (PMID 32673448, 2020). "Likewise exosome-transmitted lncARSR can promote sunitinib resistance by binding miR-34/miR-449 to facilitate AXL and c-MET expression in renal cancer, acting as a competing endogenous RNA." (PMID 32754302, 2020). "Qu et fal found that exosome transmitted lnc ARSR functioned as ceRNA sponging miR-34/miR449 that may promote the expression of AXL and c-MET, thus inducing sunitinib resistance in renal cancer." (PMID 27713133, 2017). "Exosome from sunitinib-resistant renal cancer cells could transfer lncARSR (lncRNA activated in RCC with sunitinib resistance) to sensitive cells, in which LncARSR competes with miR-34 and miR-449, promotes AXL and c-MET expression, reactivates RTKs, and mediates drug resistance." (PMID 32242003, 2020).
chronic myeloid leukemia (14 papers, 2011 to 2024). "AXL overexpression and/or activation have also been linked to Nilotinib resistance in chronic myeloid leukemia (CML) cells, and AXL expression could be a clinically relevant prognostic marker for resistance to TKI therapy in CML cells." (PMID 25337673, 2014). "The transforming gene, AXL (derived from the Greek word “anexelekto”, meaning uncontrolled) was originally isolated from chronic myelogenous leukemia cells." (PMID 25337673, 2014). "AXL, also known as UFO, was discovered from two patients with chronic myeloid leukemia in 1988." (PMID 33954117, 2021). "AXL, a transforming protooncogene, was originally isolated from chronic myelogenous leukemia cells." (PMID 28551766, 2017). "MERTK and AXL have been implicated in numerous hematopoietic malignancies, including acute leukemias (AML and acute lymphoblastic leukemia—ALL), chronic leukemias (chronic myeloid leukemia—CML and chronic lymphocytic leukemia—CLL), and multiple myeloma (MM)." (PMID 27834816, 2016). "AXL receptor tyrosine kinase (AXL-RTK) has been shown to increase tumour burden, provide resistance to therapy and is critical to maintain cancer stem cells (CSCs) in chronic myeloid leukemia (CML) by stabilizing β-catenin in the Wnt/β-catenin signalling pathway." (PMID 34140003, 2021). "AXL was isolated as a novel transforming gene from patients with chronic myelogenous leukemia; the name ‘AXL’ was derived from the Greek word for ‘non-controlled’12,13." (PMID 32051483, 2020).
clear cell renal cell carcinoma (14 papers, 2018 to 2025). "The main target molecules of cabozantinib, which was used to treat CDC in this case, are c-MET and AXL, which are strongly implicated in the pathogenesis of clear cell renal carcinoma." (PMID 40921965, 2025). "AXL has been implicated to correlate with lower response rates of anti-PD-1 blockade and worse overall survival in clear-cell renal carcinoma (ccRCC) patients who were refractory to VEGF-directed therapy." (PMID 38310091, 2024). "Our previous analysis identified key diagnostic biomarkers for clear cell renal cell carcinoma (ccRCC), and found the top 2 essential genes in LASSO regression algorithm are CA9 and AXL." (PMID 41029360, 2025). "AXL has also been identified as a direct HIF target gene in clear cell renal cell carcinoma (ccRCC)." (PMID 35158733, 2022). "In clear cell renal cell carcinoma (ccRCC), AXL expression is proved to be positively related with anti-angiogenic drug resistance and poor survival." (PMID 34123800, 2021). "This article aimed to explore the prognostic and immunological roles of AXL gene in clear cell renal cell carcinoma (ccRCC) for overall survival (OS) and to identify the LncRNA/RBP/AXL mRNA networks." (PMID 34838035, 2021). "Cabozantinib, an oral inhibitor targeting MET, AXL, and VEGF receptors, has become a key component of a sequential treatment strategy for clear cell renal cell carcinoma (ccRCC)." (PMID 38398014, 2024).
head and neck squamous cell carcinoma (14 papers, 2015 to 2025). A squamous cell carcinoma that arises from any of the following anatomic sites: lip and oral cavity, nasal cavity, paranasal sinuses, pharynx, larynx, and salivary glands. "Similar observations have been made in Head and Neck Squamous Cell carcinoma (HNSCC) when AXL, another TAM receptor was downregulated or inhibited leading to a radiosensitization." (PMID 35955805, 2022). "For example, targeting AXL successfully improved radiation response in head and neck squamous cell carcinoma (HNSCC), and it has also been found to be upregulated and activated in induced radioresistant HNSCC cell lines." (PMID 35955805, 2022). "R428 was previously shown to effectively block AXL phosphorylation and AXL-mediated cellular events, including cell migration, proliferation and angiogenesis in a variety of cancer cells, including Head and Neck Squamous Cell Carcinoma (HNSCC)." (PMID 28118606, 2017). "Interestingly, AXL activation in head and neck squamous cell carcinoma cell lines resulted in increased expression of PD-L1 and radioresistance, providing rationale for potential synergy between AXL inhibition and anti-PD-1 therapy." (PMID 31396227, 2019). "More specifically, AXL was identified as a potential therapeutic target in oral squamous cell carcinoma (OSCC), Head and Neck squamous cell carcinoma (HNSCC) and esophageal cancer, with poor prognosis correlated to high AXL expression." (PMID 28118606, 2017). "Furthermore, Brand and colleagues demonstrated that AXL is involved in acquired resistance to cetuximab in models of head and neck squamous cell carcinoma (HNSCC), in which it was overexpressed, activated and tightly associated with EGFR expression in cancer cells resistant to cetuximab." (PMID 25966280, 2015). "In NSCLC and head and neck squamous cell carcinoma (HNSCC) cells, JUN overexpression coincides with acquired resistance to cetuximab and is accompanied by increased expression of AXL." (PMID 35572601, 2022). "Similar as our results, AXL was markedly related to higher pathological grade and shorter progression-free survival in head and neck squamous cell carcinoma (HNSCC) and its overexpression could increase the resistance of HNSCC to radiotherapy, chemotherapy and cetuximab." (PMID 34838035, 2021). "Survival analysis suggests high expression of MMP10 or AXL was significantly (p < 0.05) associated with poor overall survival of head and neck squamous cell carcinoma (HNSCC) patients, but not just tongue cancer patients, which could be because there were fewer tongue cancer patients." (PMID 36650344, 2023).
myeloma (12 papers, 2019 to 2025). "This supports the notion that AXL maintains myeloma cells in a dormant state, and inhibition of AXL signalling causes myeloma cells to reactivate." (PMID 36072809, 2022). "In multiple myeloma, AXL enhances both chemotherapy resistance and dormancy in drug-resistant cells." (PMID 40715090, 2025). "AXL inhibitor treatment in mice, reduces the proportion of dormant myeloma cells and increases tumour burden, suggesting disruption of the AXL-GAS6 axis inhibits dormancy and thereby triggers reactivation." (PMID 41091336, 2025). "While these studies show disruption of AXL in myeloma, or NG2 + MSC TGF-β2 expression can reactivate dormant cells, not all cells were awakened." (PMID 41091336, 2025). "For instance, the endosteal niche helps sustain dormancy through cell-cell signaling involving the AXL tyrosine kinase, which is highly expressed by dormant myeloma cells." (PMID 41404065, 2025). "Most recently, it has been published that AXL was one of the genes enriched in a transcriptome signature of dormant myeloma cells." (PMID 38203403, 2023). "Administration of the AXL inhibitors Cabozantinib or BMS-777607 in mice with 5TGM1 tumours led to the reduction in dormant myeloma cells and an increase in reactivated cells." (PMID 36072809, 2022). "Which further substantiates AXL’s role in regulating the maintenance of dormant myeloma cells from the endosteal niche." (PMID 36072809, 2022). "SMM patients with an evolving pattern of the M-protein showed an increase in genes associated to myeloma (SLAMF7, CD79A, CD79B) and AXL." (PMID 34880879, 2021). "In a recent study, AXL was identified as a key gene highly expressed in dormant myeloma cells localized in specific niches of bones; when targeted by small molecule inhibitors, downregulation of AXL promoted cell proliferation and escape from dormancy." (PMID 31817646, 2019). "In this review, we summarize the basic functions of AXL in various cell types and the role of AXL in different hematological cancers, with a focus on AXL in the dormancy of multiple myeloma." (PMID 31694201, 2019). "Co-cultures of murine myeloma cells with osteoblasts upregulated AXL expression in myeloma PCs." (PMID 38203403, 2023). "Indeed this has been explored experimentally, where inhibiting AXL with cabozantinib or BMS777607 releases myeloma cells from dormancy, potentially sensitising cells to chemotherapeutic agents that target dividing cells." (PMID 36072809, 2022). "In MM, AXL is a potential mediator of myeloma cell dormancy and it has been hypothesized that AXL targeting would reactive dormant myeloma cells, sensitizing them to chemotherapeutic agents." (PMID 31694201, 2019). "However, recent studies also revealed an important role of AXL in lymphoid leukemia, lymphoma, and multiple myeloma." (PMID 31694201, 2019). "Anlotinib has been shown to directly target c-Myc in multiple myeloma, and reverse resistance through targeting the c-MET/MYC/AXL axis in NSCLC." (PMID 40316534, 2025). "The authors proved that GAS6, secreted by bone marrow stromal cells, activated AXL and MERTK signaling, which promoted MICA expression in myeloma cells via the NF-kB pathway." (PMID 38203403, 2023). "The number of GAS6+ and MERTK+ bone marrow plasma cells (BMPCs) were significantly increased in myeloma patients compared to healthy controls; whereas AXL and TYRO3 were mainly undetectable in BMPCs of both groups and also in human myeloma cell lines." (PMID 31694201, 2019). "Moreover, the blockade of AXL using cabozantinib and BMS-777607 in an in vivo myeloma model decreased the numbers of dormant myeloma cells, allowing them to proliferate and promote disease progression." (PMID 38203403, 2023). "Moreover, this identifies AXL as a potential biomarker for disease progression and distinguishes MGUS from myeloma patients." (PMID 36072809, 2022).
myeloma (continued). "Furthermore, expression of AXL and Gas6, a ligand that interacts with AXL were induced when cocultured with osteoblasts (MC3T3 cells) in the BM and led to the retention of myeloma cells in dormant state." (PMID 36072809, 2022).